CNTF (ciliary neurotrophic factor)
Diseases named in the same sentence as CNTF in open-access papers (continued):
Sharing a sentence is not in itself a finding about the gene and the disease.
ischemia (4 papers, 2007 to 2026). A hypoperfusion of the BLOOD through an organ or tissue caused by a PATHOLOGIC CONSTRICTION or obstruction of its BLOOD VESSELS, or an absence of BLOOD CIRCULATION. "Under those circumstances, CNTF may be a regulator of gliogenesis or gliosis, a reactive process of the glial cells following different types of insults such as ischemia, infection or malformation in the nervous system." (PMID 17563726, 2007). "Many pathologic conditions including ischemia can induce the levels of CNTF in vivo." (PMID 17563726, 2007). "The functional activity of GPCR-fAAbs may be influenced by various cofactors, including inflammation (e.g., inflammatory cytokine, ciliary neurotrophic factor (CNTF)) and ischemia." (PMID 41898657, 2026).
ischemic stroke (4 papers, 2013 to 2023). A stroke disorder caused by obstruction of blood flow to the brain, due to thrombotic (local blood clot formation) or embolic (due to a blood clot or other material traveling from another site) event. "A more recent study showed that CNTF mRNA levels were upregulated in a subset reactive astrocytes in the penumbra area at 14 days after ischemic stroke." (PMID 31105589, 2019). "Neurogenesis during AD and ischemic stroke are also related to CNTF." (PMID 33519417, 2020).
diabetic neuropathy (3 papers, 2012 to 2022). A chronic, pathological complication associated with diabetes mellitus, where nerve damages are incurred due to diabetic microvascular injury involving small blood vessels that supply these nerves, resulting in peripheral and/or autonomic nerve dysfunction. "Ocular delivery of the peptides ciliary neurotrophic factor (CNTF) or the glucagon-like peptide (GLP) analog exendin-4, both of which prevent diabetic neuropathy when given systemically, restored corneal nerve density within 2 weeks." (PMID 35566433, 2022). "NGF, IGF-I and ciliary neurotrophic factor (CNTF) are crucial players in the normal growth, maintenance and regeneration of the peripheral nervous system, but there is no such role for TGF-(1 in diabetic neuropathy." (PMID 24690397, 2014).
macular telangiectasia type 2 (3 papers, 2022 to 2025). Macular telangiectasia type 2 is a rare neurovascular degenerative retinal disease. "Another type of non-biodegradable polymeric implant device containing cells on a scaffold that release ciliary neurotrophic factor (CNTF) and is currently being evaluated for the treatment of Macular Telangiectasia Type 2 recently completed phase III clinical trials, and results are not yet posted." (PMID 38391665, 2024).
optic neuropathies (3 papers, 2021 to 2025). "Experimental studies in various disease models addressed mechanisms of action and indicated modulation of neurotrophic factors (IGF-1, BDNF, CNTF, FGF-2, TNF-α) and immunomodulators (IL-10, IL-6, COX-2, NF-κB) by electrical stimulation of the eye in optic neuropathies." (PMID 35361287, 2022).
schizophrenia (3 papers, 2020 to 2025). A major psychotic disorder characterized by abnormalities in the perception or expression of reality. "By conducting a large-sample, single-center, cross-sectional study in chronic schizophrenia, our study suggests that RNFL thickness is associated with the course of illness in schizophrenia and the concentrations of serum CNTF." (PMID 32676219, 2020). "However, caution is warranted because the association between CNTF mutation and schizophrenia remains controversial; subsequent attempts to replicate the findings have been inconclusive." (PMID 40141736, 2025). "The CNTF belongs to the neuropoietic cytokine family, playing a key role in neuronal survival and differentiation and has garnered clinical interest after reports of its possible association with schizophrenia." (PMID 40141736, 2025). "Our study showed that CNTF deficiency may cause a reduction in the retinal nerve in patients with schizophrenia." (PMID 32676219, 2020). "The alterations of the RNFL associated with decline in CNTF may represent one stage in the pathogenesis of schizophrenia, and the detailed changes and their relationship need further study." (PMID 32676219, 2020). "This study was designed to investigate retinal structural abnormalities and their correlations with CNTF and cognitive function in Chinese inpatients with schizophrenia." (PMID 32676219, 2020). "Total thickness of RNFL of both eyes significantly decreased along with decline in serum CNTF and prolonged course of schizophrenia." (PMID 32676219, 2020). "Results further showed that serum CNTF level was significantly lower in schizophrenia patients as compared to subjects in control group (1755.45 ± 375.73vs." (PMID 32676219, 2020). "CNTF was lower in the schizophrenia group (1755.45 ± 375.73 pg/ml vs. 1909.99 ± 368.08 pg/ml, p = 0.001)." (PMID 32676219, 2020). "Moreover, a total thickness of RNFL in both the eyes of schizophrenia patients was found significantly correlated with decline in serum CNTF concentration." (PMID 32676219, 2020). "On the basis of neurodevelopmental hypothesis, CNTF can be a potential protective factor of schizophrenia; however, it needs to be further investigated." (PMID 32676219, 2020). "Since serum nerve growth factor has protective effects on regional gray matter atrophy in schizophrenia, thus it is reasonable to postulate that CNTF is one the factors for neuron nutrition that may in turn prevent impairments in RNFL and cognition." (PMID 32676219, 2020). "Influence of CNTF and RNFL on the cognitive function of schizophrenia patients." (PMID 32676219, 2020). "Results revealed that MT was not significantly correlated with serum CNTF and duration of illness in patients with schizophrenia (p > 0.05)." (PMID 32676219, 2020).
spinal cord injury (3 papers, 2018 to 2021). Penetrating and non-penetrating injuries to the spinal cord resulting from traumatic external forces (e.g., WOUNDS, GUNSHOT; WHIPLASH INJURIES; etc.). "First, CNTF was found to be required for axonal regeneration after spinal cord injury (SCI) 25, 27-29." (PMID 34345208, 2021).
autism (2 papers, 2015 to 2020). Persistent deficits in social interaction and communication and interaction as well as a markedly restricted repertoire of activity and interest as well as repetitive patterns of behavior. "Previously, increased oxidative stress which is widely implicated in the pathophysiology of autism was shown to block CNTF activity in neurons which is essential for neuronal survival and maintenance." (PMID 25769033, 2015). "The levels of mature CNTF and BDNF were markedly decreased in autism sera (CNTF, Student’s t-test, p = 0.0026; BDNF, Student’s t-test, p = 0.0003)." (PMID 25769033, 2015). "The serum levels of CNTF were found to be lower and the levels of FGF-2 and LIF were found to be higher in children with autism compared to age-matched healthy controls." (PMID 25769033, 2015).
brain tumor (2 papers, 2011 to 2017). "Ciliary neurotrophic factor receptor α subunit (CNTFRα) and CNTF play important roles in neuron survival, glial differentiation and brain tumor growth." (PMID 28765641, 2017). "Other growth factors involved in brain tumors are insulin-like growth factors, IGFs fibroblast growth factor 2, FGF2, ciliary neurotrophic factor, CNTF, hepatocyte growth factor/scatter factor, HGF/SF, vascular endothelial growth factor, VEGF, and transforming growth factor-β, TGF-β." (PMID 22091432, 2011).
dementia (2 papers, 2021 to 2023). Loss of intellectual abilities interfering with an individual's social and occupational functions. "Other growth factors, notably ciliary neurotrophic factor (CNTF) and GDNF, are also interesting molecules because of their role in the progression of dementia." (PMID 34199883, 2021).
demyelinating disease (2 papers, 2013 to 2016). A broad group of disorders that affect the myelin sheaths that cover the neurons. "In addition, CNTF was identified within activated/reactive astrocytes in and around spinal cord remyelinating lesions, and regulated FGF-2 production in astrocytes during early remyelination, suggesting CNTF as an important cytokine in demyelinating diseases." (PMID 27551677, 2016).
demyelination (2 papers, 2015 to 2023). "Ciliary neurotrophic factor (CNTF), a pleiotropic cytokine within the IL-6 family, has been shown to promote spinal cord-derived OPCs survival and differentiation in culture as well as endogenous OPCs migration in an acute demyelination model." (PMID 26491661, 2015).
developmental delay (2 papers, 2016 to 2017). "Here, we report that prenatal to early postnatal treatment with a ciliary neurotrophic factor (CNTF) small-molecule peptide mimetic, Peptide 021 (P021), rescued developmental delay in pups and AD-like hippocampus-dependent memory impairments in adult life in Ts65Dn mice." (PMID 28368015, 2017). "CNTF and LIF promote oligodendrocyte differentiation in vitro, however, CNTF knockout and LIF knockout mice only have a developmental delay in oligodendrogenesis, indicating that these factors may be a mediator of oligodendrogenesis early in development." (PMID 27895617, 2016).
focal epilepsy (2 papers, 2022 to 2023). A seizure caused by a localized disorder. "Particularly, in patients with focal epilepsy, CNTF levels were increased, while BDNF levels decreased both in the blood serum (BS) and LF, suggesting that high CNTF levels and low BDNF levels in the LF could be considered as non-invasive biomarkers of focal epilepsy." (PMID 38069144, 2023).
Hepatic steatosis (2 papers, 2020 to 2022). Steatosis is a term used to denote lipid accumulation within hepatocytes. "Treatment with CNTF significantly improved hepatic steatosis and serum markers of hepatic inflammation." (PMID 32175323, 2020). "CNTF improved hepatomegaly, hepatic steatosis, and inflammation." (PMID 32175323, 2020). "Increased expression of neurotrophic factors including GDNF, CNTF, BDNF, and NRG4 all alleviate hepatic steatosis." (PMID 32175323, 2020).
injury (2 papers, 2010 to 2013). Damage inflicted on the body as the direct or indirect result of an external force, with or without disruption of structural continuity. "CNTF is produced by glial cells, as well as some neurons, to exert a neuroprotective role after various causes of nerve injury or stresses." (PMID 23626705, 2013). "A recent study by Hauk and colleagues showed that intravitreal injection of toll-like receptor 2 agonist Pam3Cys (caused lens injury) can induce glial activation and upregulations of GFAP and CNTF, which significantly stimulated retinal ganglion cell axon regeneration into the injured optic nerve." (PMID 20169166, 2010).
memory impairment (2 papers, 2016 to 2022). "Furthermore, BDNF and CNTF play crucial roles in the survival of neuronal cells associated with memory impairment." (PMID 35076339, 2022).
morbid obesity (2 papers, 2020 to 2022). An excess of body weight, normally defined as an individual with a body mass index greater than 35 or a body weight greater than one hundred percent of ideal body weight. "Investigation of the multiple, redundant mechanisms by which CNTF induces a reduction in food intake has the potential to suggest novel treatments for morbid obesity." (PMID 32528252, 2020).
motor neuron degeneration (2 papers, 2016 to 2023). "Further findings strengthened the beneficial effect of CNTF in a motor-neuron degeneration mouse model of neuronopathy." (PMID 27898033, 2016). "CNTF has been found to affect motor neuron survival in vitro, during development, after injury to motor neuron systems, and in genetic models of motor neuron degeneration, providing a rationale to develop CNTF as a treatment for ALS and SCI, in which ventral motor neuron degeneration is extensive." (PMID 36835277, 2023).
neuroendocrine tumor (2 papers, 2013 to 2018). "EGF and CNTF direct fusions were as active on the neuroendocrine tumor cells as the stapled products in terms of selectivity and cleavage of SNAP25." (PMID 23638840, 2013). "Here, we investigated TNFα, CNTF, EGF, dermorphin, dynorphin 17, substance P, somatostatin, corticotropin-releasing hormone, and the native botulinum receptor-binding domain for their ability to direct the botulinum protease into a variety of neuroendocrine tumor cells." (PMID 23638840, 2013).
ocular hypertension (2 papers, 2021 to 2022). Abnormally high intraocular pressure. "Intravitreal CNTF protein has a short half-life, though AAV delivery of CNTF protects RGCs from ocular hypertension." (PMID 34200991, 2021).
rheumatoid arthritis (2 papers, 2004 to 2021). A chronic, systemic autoimmune disorder characterized by inflammation in the synovial membranes and articular surfaces. "Although LIF and CNTF have been shown in rodent studies to induce an acute phase protein response and weight loss our results are consistent with the largely undetectable levels reported in patients with rheumatoid arthritis." (PMID 15570310, 2004).
Strabismus (2 papers, 2020 to 2024). A misalignment of the eyes so that the visual axes deviate from bifoveal fixation. "Evidence suggested that alterations in CNTF levels might play a role in the development and/or maintenance of strabismus, where studies suggested it is differentially expressed in the extraocular muscles from individuals with strabismus." (PMID 39330989, 2024). "As the muscles used for analysis were from individuals with strabismus and age-matched controls, it is unclear whether the altered levels of CNTF were primary or secondary to other changes in the neurotrophic factor milieu in individuals with strabismus." (PMID 39330989, 2024). "Little is known about the effect of ciliary neurotrophic factor (CNTF) on extraocular muscles, but microarray studies suggested CNTF might play a role in the development and/or maintenance of strabismus." (PMID 39330989, 2024). "Decreased levels of CNTF, GDNF, as well as altered levels of IGF binding proteins, which are inhibitory in function, shown in the microarray studies suggest that increasing the levels of a single neurotrophic factor is likely to be insufficient to generate or treat a large angle strabismus." (PMID 32681083, 2020).
type 1 diabetic (2 papers, 2016 to 2023). "Hence, in the case of the STZ-induced type 1 diabetic mice with corneal epithelial debridement wounds, decreased number of DCs on the cornea would lead to a decreased CNTF level, impairing corneal sensory nerve innervation and regeneration." (PMID 36777336, 2023).
achromatopsia (1 paper, 2013). Achromatopsia (ACHM) is a rare autosomal recessive retinal disorder characterized by color blindness, nystagmus, photophobia, and severely reduced visual acuity due to the absence or impairment of cone function. "Intravitreal delivery of recombinant CNTF has also recently been shown to significantly enhance the efficacy of gene augmentation therapy in the treatment of achromatopsia." (PMID 24278479, 2013).
astroglioma (1 paper, 2013). "The integrin substrates laminin, fibronectin and vitronectin, but not collagen, thrombospondin or fibrinogen, reduced CNTF expression in C6 astroglioma cells." (PMID 23693126, 2013).
auditory neuropathy (1 paper, 2022). A hearing disorder characterized by impaired transmission of signals through the auditory nerve, resulting in mild to severe hearing loss and poor speech perception. "Neurotrophic factors such as BDNF, CNTF, NT3, and NGF have been tested in animal models of auditory neuropathy in different studies." (PMID 35720065, 2022).
bent bone dysplasia (1 paper, 2022). "The SWS is characterized by a combination of symptoms with bone involvement and dysautonomic disturbances, therefore the disease is classified in both groups of skeletal dysplasias (subgroup of bent-bone dysplasias) and ciliary neurotrophic factor (CNTF) pathway related disorders." (PMID 35461249, 2022).
Charcot-Marie-Tooth disease type 1A (1 paper, 2013). Charcot-Marie-Tooth disease type 1A (CMT1A) is a type ofinherited neurological disorder that affects the peripheral nerves. "Furthermore, reduced expression of CNTF in SCs is observed in the most common form of hereditary peripheral neuropathy (Charcot-Marie-Tooth Disease type 1A (CMT1A)), which is characterized by axonal atrophy." (PMID 24391540, 2013).
colitis (1 paper, 2014). Inflammation of the colon. "Due to its low affinity, CNTF is unlikely to play a role as the IL-6R ligand that influences the susceptibility to DSS-induced colitis in mice." (PMID 24993179, 2014). "CNTF and p28 may play a beneficial role in DSS-induced colitis, as well as another unknown ligand for the IL-6R." (PMID 24993179, 2014).
deafness (1 paper, 2011). An inherited or acquired condition characterized by the complete loss of the ability to hear from one or both ears. "And lastly, the G. gallus genome had extreme codon bias for the Ciliary Neurotrophic Factor – which may help to explain their spontaneous recovery from deafness." (PMID 21966531, 2011).
endometriosis (1 paper, 2023). The growth of functional endometrial tissue in anatomic sites outside the uterine body. "Additionally, it is worth noting that other IL-6 family proteins (such as ciliary neurotrophic factor (CNTF) and oncostatin-M (OSM)) use the LIF receptor for signaling and have been implicated in various aspects of endometriosis." (PMID 37033980, 2023).
endothelial dysfunction (1 paper, 2025). In vascular diseases, endothelial dysfunction is a systemic pathological state of the endothelium (the inner lining of blood vessels) and can be broadly defined as an imbalance between vasodilating and vasoconstricting substances produced by (or acting on) the endothelium. "Knockdown of CNTF mitigates these effects by reducing inflammation and apoptosis, suggesting that targeting the CNTF-MAFK axis could serve as a potential therapeutic strategy for preventing endothelial dysfunction and CVDs associated with HHcy." (PMID 39898976, 2025).
endotoxemia (1 paper, 2022). "Ciliary neurotrophic factor (CNTF) has been shown to protect against LPS induced endotoxemia and reduce TNFα production, and may also increase M2 macrophage differentiation." (PMID 36478877, 2022).
Hepatic fibrosis (1 paper, 2020). The presence of excessive fibrous connective tissue in the liver. "The role of CNTF and BDNF in hepatic fibrosis is not understood." (PMID 32175323, 2020).
insulinoma (1 paper, 2013). "In the Min6 insulinoma cells the pattern changed, the BoT-Staple-EGF was as efficient as Bitox whereas CNTF and CRH moieties were less effective." (PMID 23638840, 2013).
intracerebral hemorrhage (1 paper, 2015). A cerebrovascular disorder characterized by bleeding into one or both cerebral hemispheres including the basal ganglia and the cerebral cortex. "Moreover, levels of CNTF and CNTFRα could increase in the brain following injury, such as focal cerebral ischemia and intracerebral hemorrhage." (PMID 25799580, 2015).
keratoconus (1 paper, 2022). A degenerative, structural disorder of the eye, characterized by a cone-shaped protrusion of the cornea. "Another neurotrophin, ciliary neurotrophic factor (CNTF) which is important for protection of the cornea from oxidative radical damage, had a higher expression of its mRNA in keratoconus as compared to normal eyes." (PMID 35054085, 2022).
leukemia (1 paper, 2021). A malignant (clonal) hematologic disorder, involving hematopoietic stem cells and characterized by the presence of primitive or atypical myeloid or lymphoid cells in the bone marrow and the blood. "CNTF, which is a pluripotent neurotropic factor and is related with the cytokine family that includes IL-6, IL-11, leukemia inhibitory family, and oncostatin, binds and signals to maintain the bone homeostasis through the gp130 coreceptor subunit." (PMID 33833854, 2021).